NES (nestin)
Diseases named in the same sentence as NES in open-access papers (continued):
Sharing a sentence is not in itself a finding about the gene and the disease.
tumor (continued). "Ctdnep1 ablation in Nestin+ NPCs causes extensive cell death in the developing brain, which may contribute to animal death prior to tumor formation, suggesting that additional genetic, epigenetic, and other molecular events are necessary prior to full transformation." (PMID 36765089, 2023). "In series 1, weak E‐cadherin expression and the EN‐switch were associated with maximum Nestin micro‐vessel density (Mann–Whitney, p = 0.042 and p = 0.003), increased vascular proliferation by Nestin‐Ki67 and high tumour cell proliferation by Ki67 (Mann–Whitney p = 0.032 and p = 0.051)." (PMID 31464093, 2019). "As Nestin expression is tightly correlated to tumor malignancy, elucidating the underlying mechanisms through which Nestin is regulated and exerts its antioxidant function may suggest therapeutic targets in efforts to abrogate tumor growth and restore chemosensitivity." (PMID 31695040, 2019). "Thus, Nestin deficiency inducing tumor senescence indicates Nestin might be a therapeutic target for tumor treatment." (PMID 30190500, 2018). "Also, Nestin was associated with gene expression patterns indicating stem-like tumour features." (PMID 28439082, 2017). "Classical pericyte and SMC markers were generally comparable across the regions in the mouse model, except for an elevation of Nestin in the tumor." (PMID 40674254, 2025). "Immunohistochemistry showed that both the spindle and granular-like tumor cells were positive for Nestin, Leu-7, PGP9.5, CD56 and BCL2." (PMID 41179673, 2025). "Immunoreactivity for CD56, Leu-7, PGP9.5 and Nestin was observed in both tumor components, which suggested a neural crest origin." (PMID 41179673, 2025). "Tumor cells in mETMR-FBO (NES+, some expressing nuclear β-Catenin) and hETMR-FBO (NES+; LIN28a+) recapitulated the major histopathological features of primary ETMR, including a similar neuronal differentiation profile." (PMID 40562749, 2025). "Nitidine chloride can inhibit the expression of nestin, a tumor CSC related factor, through the Hedgehog pathway." (PMID 40799240, 2025). "In this context, it is important to mention that, until now, nestin-positive tumor blood vessels are interpreted as angiogenic blood vessels." (PMID 40149541, 2025). "These highlights nestin as a promising therapeutic target for limiting tumor aggressiveness and improving treatment outcomes." (PMID 40799240, 2025). "Beyond tumor angiogenesis, nestin is expressed in physiological angiogenesis, such as in the pancreas, skin, and corpus luteum." (PMID 40149541, 2025). "Some endothelial cells of microvessels (identified by colocalization with Glut-1) in tumour cell dense regions also showed nestin expression." (PMID 40414994, 2025). "Future research should be focused on developing efficient and specific tumor-targeting delivery systems for the precise delivery of anti-nestin therapeutic agents." (PMID 40799240, 2025). "In the selected HGG samples (n = 3), multiplex immunofluorescence staining confirmed only limited colocalization of PSMA with the marker nestin, i.e., with neuroepithelial stem cells including tumour cells, in line with the immunohistochemistry results." (PMID 40414994, 2025). "At 21 days post-implantation, the degree of tumor invasion was assessed histologically in brain sections stained with nestin antibody." (PMID 39682088, 2024). "C3 was present primarily in perivascular and perinecrotic (hypoxic) tumor niches, in close proximity to Nestin-expressing cells." (PMID 39172519, 2024). "The readout included human CD14 (myeloid cells), EGFRvIII (antigen-positive tumor cells), and NESTIN (pan-GBM cell marker) IF stainings." (PMID 39521782, 2024). "When comparing MVD measured by Nestin, and that measured by CD34, the first one showed more significant associations with larger tumor extent, and advanced tumor stage (P=0.001, 0.001 versus 0.006 and 0.009)." (PMID 39687450, 2024).
tumor (continued). "Human-specific Nestin staining revealed the presence of cells invading the corpus callosum and cortex at this stage of the tumor." (PMID 38166949, 2024). "The data suggest that at least one of the three Trk receptors is immature and phospho-active in this specific Nestin+ tumor sample." (PMID 39039193, 2024). "So, the detection of proliferating newly formed BV by Nestin appeared to be a better predictor for tumor metastasis and survival." (PMID 39687450, 2024). "This study revealed that Nestin and FLT1 expressions in RCC were significantly associated with aggressive tumor parameters." (PMID 39687450, 2024). "To understand the role of C3 and complement in the tumor microenvironment, we returned to stain the murine GBMs for C3, GFAP, Olig2, and Nestin to highlight perivascular tumor areas." (PMID 39172519, 2024). "Nestin is also expressed in various types of malignancies such as osteosarcoma, NB, glioma melanoma, and pancreatic and prostate cancers, especially in tumor vasculature." (PMID 38925618, 2024). "The immunofluorescence assay indicated more aggregated nestin in the GSCs tumor nests, which illustrated the maintained stemness of GL261-GSCs in vivo." (PMID 39061140, 2024). "Although IE staining was present only in the tumor core, nestin was detected both in the tumor core and the invasive part." (PMID 38553638, 2024). "Consistent with the scRNA-seq data, the ectopic NRAS level tended to be higher in the NOTCH1/nestin+ tumours." (PMID 39112713, 2024). "Nestin was expressed mainly in endothelial cells of small vessels in 65% of cases while FLT1 was expressed in tumor and endothelial cells in 73.3% of cases." (PMID 39687450, 2024). "CD105 and Nestin were both positively expressed of the T24 spheres, indicating high stemness of the tumor spheres." (PMID 37789353, 2023). "HE staining, in conjunction with nestin and synaptophysin staining, was carried out to assess the extent of the tumor mass." (PMID 36993983, 2023). "Of note, nestin was strongly expressed not only on tumor cells but also on the peritumoral astrocytic population (black arrowheads)." (PMID 36993983, 2023). "Here, we showed that tumor treatment with Vern extract or phytol resulted in the elimination of CSCs, as indicated by the decreased expression of the specific markers Nestin and Sox2." (PMID 36900417, 2023). "The IF staining for Sox2 and Nestin of the tumor specimens demonstrated that in tumors treated with plant Vern extract or phytol, the expression levels of these CSC markers was highly reduced, by about 70%." (PMID 36900417, 2023). "Our study provided chemically defined media and culture conditions that led to the enrichment of Nestin+ tumor stem/progenitor cells and the formation of a tumor growth niche in both 2D and 3D." (PMID 37508868, 2023). "AOT expressed ALDH1, CD44, c-Myc, and Nestin, mainly in epithelial cells of tumor nests and rosette-like structures." (PMID 37761874, 2023). "In the 3D silk fibroin-based scaffolds, individual tumor cells developed Nestin and Ki67 double-positive tumor spheroids." (PMID 37508868, 2023). "After the infusion of ECM gels into the scaffold, the tumor cells spread and migrated to fill the pores with dense and extensive Nestin+ and GFAP+ processes." (PMID 37508868, 2023). "We observed that, in all pHGG models, tumor cells remained similarly Nestin-positive and SOX2-positive in all investigated brain areas, including the pons, cerebellum and SVZ." (PMID 37328883, 2023). "Regarding these soluble factors, we found that the serum was harmful by inducing fibroblast-like cell overgrowth, suppressing Nestin+ tumor cells, and 3D culture viability." (PMID 37508868, 2023).
tumor (continued). "Markers for proliferation (Ki-67) and stemness (Nestin) were analyzed by immunofluorescence staining, revealing expression of Ki-67 predominantly in the outer layer, whereas Nestin appeared widely expressed throughout the tumor organoid." (PMID 37508520, 2023). "Interestingly, the results of the subgroup also suggested that differences in tumor type may significantly affect the association between nestin and survival outcomes in patients with DTCs, which may be a potential source of heterogeneity among the included studies." (PMID 37485559, 2023). "IF staining on tumor sections revealed high levels of NESTIN expression in the mock-BBZ CAR-T group, but very low levels in the Pep42-BBZ CAR-T group." (PMID 37481592, 2023). "For example, Nestin, which labels NSCs in adult mouse brain, also marks BTICs in glioblastoma and is required for the long‐term sustenance of tumour growth." (PMID 36321378, 2023). "SOX2+Nestin+ cells were abundant within the tumor boundary but only sporadically outside of the tumor." (PMID 36038950, 2022). "Its protein expression level is positively correlated with the degree of malignancy of tumor, so the expression level of Nestin in tumor tissues is of great significance for evaluating the biological behavior of tumors and the prognosis of patients." (PMID 37786888, 2022). "First, small RNA libraries for paracarcinoma tissues (Normal) and ESCC tissues (Tumor) were constructed and sequenced to reveal Nestin-related miRNAs." (PMID 35370458, 2022). "Stemness markers, SOX2 and nestin, were differentially expressed in tumor cells at the invasive margin." (PMID 35312755, 2022). "In DFS treated TS, expression of Nestin, the marker of stemness, was downregulated and tumor edges were soother than TS untreated group." (PMID 35978012, 2022). "Nestin positive cells mark the existence of a stem cell-like population, which enables tumor cells to continue to survive and differentiate." (PMID 35444938, 2022). "Nestin is a member of the intermediate fiber family, and its expression increases in a variety of tumor tissues." (PMID 37786888, 2022). "The size of the tumour was analysed using nestin immunostaining and was significantly lower in xenograft mice treated with regorafenib compared to untreated xenograft mice (4.37 ± 1.16 vs. 12.33 ± 3.02 mm2, p < 0.05)." (PMID 35326702, 2022). "Tumor cells within the PD-GBO form a morphological interconnecting tumor network proficient for nestin, Gap43, Connexin 43, and the astrocytic marker GFAP." (PMID 35743016, 2022). "Patients with high rates of Nestin expression within the primary tumor tended for worse prognosis as did patients with an increased amount of CD133 positive tumor cells in recurrence." (PMID 35183162, 2022). "Of the 5 groups, tumor volume was the smallest in the miR-204-5p overexpression group while that was largest in the Nestin overexpression group." (PMID 35370458, 2022). "Tissue microarrays of tumor samples for patients between 2007 and 2016 were used for immunodetection of Nestin, SOX2, SOX9, KLF4, NANOG, CD133 cMYC, and Ki67." (PMID 35795469, 2022). "Given the clinical rates of CSF pathway spread in DIPG, we evaluated CSF–tumor–ependyma interactions in a Nestin-tumor virus A (Nestin-Tva)-based GEMM of DIPG." (PMID 35733516, 2022). "Both Sox2+Nestin+ and CD105+Nestin+ cell populations exist in this area, but CD105+Nestin+ cells were more numerous and locate around angiogenic tumor capillaries." (PMID 36038950, 2022). "High expression of nestin in GBM cells identifies a sub-population of tumor-initiating cells responsible for high malignancy, chemo-resistance and relapse." (PMID 35326570, 2022). "Tumor spheroids in 3D models contained significantly more Nestin+ (9.4 ± 1.2%) and CD133+ (putative cancer stem cell, 7.4 ± 1.1%) cells than 2D cultures (0.6 ± 0.4% and 2.4 ± 0.7%, respectively)." (PMID 35381525, 2022).
tumor (continued). "Post-mortem mice brains underwent immunohistochemistry staining for ASCT2 (amino acid transporter), nestin (stemness) and Ki-67 (proliferation) to assess for biologically active tumour." (PMID 35884545, 2022). "Nestin plays an essential role in the resistance against conventional chemotherapy of tumor stem cells." (PMID 35444938, 2022). "In contrast, numerous CD105+Nestin+ cells resided both within the tumor bulk and in the peritumor vascular structures." (PMID 36038950, 2022). "The degree of cell differentiation and tumor vascularization were evaluated using the Nestin marker, observing immunoreactivity in 62.50% of cases." (PMID 36290853, 2022). "Tumor cells with Nestin and Fascin double-positive expression were detected in the double immunofluorescence staining of Nestin and Fascin." (PMID 35054386, 2022). "The molecular details involved in the role of nestin in tumor behavior still require further clarification." (PMID 34943921, 2021). "The expression level of Nestin in the tumor specimens (n = 8) of mice in each group was also examined." (PMID 34772403, 2021). "Nestin positivity was observed not only in tumor cells but also in vascular endothelial cells and in tumor stromal fibroblasts." (PMID 34943921, 2021). "Nestin positivity was related to tumor differentiation and lymphatic metastasis, and was an independent prognostic factor for OS after controlling for confounding factors." (PMID 34943921, 2021). "For nestin labelling, when GlioGel with chemokine is inoculated in the tumor, we observed an increase compared to the control GlioGel." (PMID 34830041, 2021). "Like the parent tumor, 2XSB cells were immunoreactive for Sox10 (80–100% positivity), nestin (90–100% positivity) and S100β (80–100% positivity)." (PMID 33707600, 2021). "This study determined the effect of Nestin on in vivo tumor formation and in vitro tumor phenotypes (proliferation and metastasis) during GC development and the underlying mechanism." (PMID 34772403, 2021). "Western blotting of tumor tissues demonstrated efficient SOX2/Nestin suppression in SB273005 or SB273005/TMZ groups compared to the control or TMZ group." (PMID 33408794, 2021). "Other intracellular markers, S100β and Nestin were expressed at similar intensity but in a lower proportion of tumours (70% and 60%, respectively)." (PMID 34885099, 2021). "Simultaneously, increased expression of CD133 and nestin in high-grade tumor tissues lead to an increase of cell atypia and reduced effectiveness of medical treatment." (PMID 33284535, 2021). "Nestin + cells present at the tumor margin survived TMZ therapy, recovered from the chemotherapy-induced growth arrest, and reconstituted the tumor leading to recurrence." (PMID 33805316, 2021). "Nestin has been found to be involved in cell migration, as it is localised in the leading edge of the tumour." (PMID 33637089, 2021). "In conclusion, this study confirmed the interaction between the Keap1–Nrf2 axis and Nestin and that Nestin can mediate antioxidant responses and maintain tumor phenotypes in GC." (PMID 34772403, 2021). "The expression level of nestin increases in various tumor cells and its expression proliferates vascular ECs." (PMID 34503252, 2021). "Nestin was also lower in patients with large tumor size at presentation (>/= 5 cm) than small tumor size (tumor size taken at largest diameter); median 27, 31.6 pg/mL, respectively." (PMID 33584136, 2021). "Although cells expressing DCX lacked this correlation, there was a strong negative correlation between the frequency of DCX+ cells in the margin and the frequency of NES+ cells both in tumour and margin sites." (PMID 34948016, 2021).
tumor (continued). "Other occasionally reported factors included tumour distribution (peripheral or central), pneumonectomy, plasma albumin concentration, NSE concentration, C-kit protein expression, Nestin expression and EGFR mutation." (PMID 33579331, 2021). "Since the tumor sphere formation and the expression of Nestin and SOX2 are the characteristics of GSCs, these results suggest that RPS6 plays critical roles in the development and maintenance of GSCs." (PMID 35008473, 2021). "The mice were subcutaneously injected with SGC-7901, SGC-7901-sh-NC, and SGC-7901-sh-Nestin cells to investigate the role of Nestin using a xenograft of GC tumor growth." (PMID 34772403, 2021). "Immunocytochemistry further revealed co-expressions of CD44 and CD133 as well as Nestin in isolated CSCs, independently to the tumor origin." (PMID 33800955, 2021). "Only one case showed an extensive (+++) positivity for nestin, both in the tumour cells and stromal fibroblasts." (PMID 33917771, 2021). "Previous reports have provided insights into the molecular mechanisms of Nestin in tumor development." (PMID 34772403, 2021). "An in vivo tumorigenesis experiment further demonstrated the influential role of Nestin during tumor growth, which indicates the mechanisms underlying Nestin modulation and exertion of antioxidant effects as well as the potential treatment targets that may be used to prevent tumor growth." (PMID 34772403, 2021). "We also evaluated the correlations between the expression of DCX, OLIG2, and NES genes at a single-cell level in the population of cells derived from the tumour tissue to show the potential relation of these genes." (PMID 34948016, 2021). "The involvement of the Keap1–Nrf2 axis in the Nestin-modulated antioxidant response and tumor phenotypes (proliferation and metastasis) of GC was also elucidated." (PMID 34772403, 2021). "A subset of tumor cells was immunoreactive for the intermediate filament nestin (30–70% of the cells in each field), much as was observed for the calcium binding protein S100β (30–70% positivity)." (PMID 33707600, 2021). "siRNA has been shown to exert a tumor-suppressive effect in vivo by inhibiting tumor angiogenesis, suggesting that Nestin is a novel treatment target for many types of tumors." (PMID 34772403, 2021). "We also showed that Nrf2 overexpression or SF treatment in GC cells counteracted the effect of Nestin knockdown on tumor phenotypes and antioxidant capacity." (PMID 34772403, 2021). "Densitometric analysis of the agarose gel electrophoresis of the PCR products from normal uvea samples showed considerably lower positivity compared to tumor samples (nestin: p = 0.007; SOX10: p = 0.004)." (PMID 33255843, 2020). "These tumours were positive for nestin, indicating that constitutive cells are of neuronal stem cell specification." (PMID 32404936, 2020). "rQNestin34.5 is a an engineered oHSV based on F-strain HSV1 that expresses the neurovirulence factor ICP34.5 under a synthetic nestin promoter to drive robust tumor-selective viral replication." (PMID 33255871, 2020). "Nestin+ tumor cells have been observed to be the origin of tumor regrowth after chemotherapeutic treatment with the alkylating agent temozolomide." (PMID 33260962, 2020). "Surface modifications with targeting ligands such as angiopep‐2 and nestin have been employed to achieve even greater tumor accumulation, a strategy we are exploring to further improve the tumor targeting of these PAMAM dendrimers." (PMID 32440565, 2020). "Analyses of in vivo orthotopic tumor also indicated that 100% of SOX2+ or Nestin+ GSLCs were BPA+, whereas only 36.9% of glial fibrillary acidic protein (GFAP)+ DCs were BPA+." (PMID 33086625, 2020). "Accumulated evidence suggested that nestin expression in the blood vessels is basically localized to the newly formed endothelial cell of tumor vessels." (PMID 32467665, 2020).